CD4 (CD4 molecule)
Diseases named in the same sentence as CD4 in open-access papers (continued):
Sharing a sentence is not in itself a finding about the gene and the disease.
pancreatic cancer (continued). "Similar results were demonstrated in a study using a pancreatic cancer model which showed increased CD4+ T cells and decreased Tregs when animals were fed a KD." (PMID 27178315, 2016). "The development of strategies based on immunonutrition, recombinant IL-7, to expand CD4 T cells and the preliminary results of novel immunotherapies, offer new therapeutic endpoints to be assessed in pancreatic cancer patients." (PMID 27782813, 2016). "Multivariate survival analysis revealed that tumour infiltrating CD4+ Thigh/CD8+ Thigh/%Treglow significantly correlated with longer survival time in 212 pancreatic cancer samples." (PMID 26415232, 2015). "In particular, CD4+CD25+ Treg percentages are elevated in the peripheral blood of pancreatic cancer patients as well as lymphoid organs in mice." (PMID 25629611, 2015). "They reported that higher levels of CD4+ and CD8+ tumor-infiltrating lymphocytes in pancreatic cancers were associated with longer overall survival after surgical resection." (PMID 24612467, 2014). "The number of peptide pools stimulating antigen specific IFN-γ production by CD4+ or CD8+ T cells in 25 patients with pancreatic cancer, 15 patients with benign pancreatic disease and 16 healthy donors are shown." (PMID 24520352, 2014). "MSLN21–35 LLFLLFSLGWVGPSR was recognized by CD4+ T cells in 5 out of 14 patients with pancreatic cancer or benign pancreatic disease." (PMID 24520352, 2014). "An anti-MSLN CD4+ T cell response was observed in 84% of pancreatic cancer patients (21 out of 25), 66.7% of patients with benign disease (10 out of 15) and 43.7% of healthy donors (7 out of 15)." (PMID 24520352, 2014). "We aimed to assess the status of naturally occurring CD4+ and CD8+ T cell responses to a tumour associated antigen, Mesothelin, in patients with pancreatic carcinoma and study the effects of elevated IL-10 on Mesothelin-specific T cell responses." (PMID 24520352, 2014). "It should be emphasized that the percentage of conventional T cells (Tcon, CD4+FoxP3−) had been reduced in the spleen and increased in the tumor of the tumor-bearing mice with pancreatic carcinoma, indicating a possible migration of Tcon to the tumor site." (PMID 24608924, 2014). "Pancreatic tumors in TNFR1 deficient mice displayed increased vascular density, enhanced infiltration of CD4+ T cells and CD4+ forkhead box P3 (FoxP3)+ regulatory T cells (Treg) but reduced numbers of CD8+ T cells." (PMID 24098720, 2013). "We previously reported that pancreatic cancer patients have a selective Th2 skew in the anti-carcinoembryonic antigen (CEA) CD4+ T cell immunity, which correlates with the presence of a predominant GATA-3+ tumor lymphoid infiltrate." (PMID 19798410, 2009). "Collectively, our results demonstrate that tumor antigen specific Th2 CD4+ T cells in pancreatic cancer are endowed with functional plasticity." (PMID 19798410, 2009). "To determine the potential relevance of B7-H3 expression on the distribution of CD4+ or CD8+ T cells in pancreatic cancer, we first examined mRNA levels of CD4 and CD8 in 28 pancreatic cancer tissue specimens and 10 normal pancreatic tissue specimens." (PMID 20035626, 2009). "In addition, IHC analysis showed significantly higher expression of CD4, CD8a and PD-1 in orthotopic pancreatic cancer sections in the THM + αPD-1 group compared with the vehicle group, THM and αPD-1 groups." (PMID 40756353, 2025). "We also detected cell line–specific chemotactic patterns: CD4+ T cell migration increased toward irradiated PANC-1 pancreatic cancer cells (1.39-fold, P = 0.021), whereas CD8+ T cell chemotaxis increased toward irradiated SJSA-1 osteosarcoma cells (1.26-fold, P = 0.029)." (PMID 40811032, 2025). "Conversely, other phenotypes, including CD28 on CD45RA− CD4 non‐Treg (OR = 1.155, 1.028–1.297, p = 0.016) and CD25 on activated Treg (OR = 1.180, 1.014–1.374, p = 0.032) within T regulatory cells, exhibited a positive correlation with pancreatic cancer risk." (PMID 39906083, 2025).
pancreatic cancer (continued). "In addition to tumor intrinsic chromatin signatures, our data revealed differential cfDNA enrichment at CD4+ T cell specific open chromatin regions in both breast and pancreatic cancer patients." (PMID 41225146, 2025). "We developed an in vitro stimulation approach and identified HLA-A*11:01–restricted KRAS G12V–reactive CD8+ T cells and HLA-DRB1*15:01–restricted KRAS G12V–reactive CD4+ T cells from peripheral blood of 2 out of 6 HLA-A*11:01–positive patients with pancreatic cancer whose tumors expressed KRAS G12V." (PMID 39846249, 2025). "PRC1 was overexpressed in pancreatic cancer and negatively correlated with CD4+ T cells." (PMID 39409930, 2024). "Similarly, in a pancreatic cancer model, the deletion of Tregs resulted in decreased expression of Col and Fn1 mRNA in CAFs, accompanied by increased infiltration of effector CD4 + and CD8 + T cells." (PMID 38684596, 2024). "In the pancreatic cancer microenvironment, Tregs account for almost 25% of the total CD4+T cells." (PMID 39235042, 2024). "Interestingly, although CD4-positive T cell ablation enables CD8-positive T cell-mediated deterioration of pancreatic tumors in mice, consumption of FOXP3-positive Tregs accelerates tumorigenesis as a result of compensatory myeloid infiltration." (PMID 38352864, 2024). "Thus, identification of extracellular markers to identify tumor-reactive CD4+ T cells in pancreatic cancer warrants further investigation." (PMID 38335302, 2024). "Treatment with CXCR1/2 inhibitor SX-682 dramatically depleted the population of intratumoral CXCR2+ MDSCs and increased the infiltration of CD8+ and CD4+ T cells to suppress pancreatic cancer growth in a mouse iKRAS PDAC model, enhancing the survival time of tumor-bearing mice." (PMID 38672552, 2024). "Antigen-presenting CAFs are another type of immune-modulating fibroblast that express MHC class II and modulate CD4+ T-cells and it has been suggested that peritoneal mesothelial cells may be progenitors of antigen-presenting CAFs in pancreatic cancer." (PMID 38212075, 2024). "In patients with pancreatic cancer, a mutated Ras‐SLP was aimed to predominately activate CD4+ T cells can be synergized with GM‐CSF and mediate a robust CD4+ T cell response to prolong survival, underlining the crucial role of MHC‐II‐restricted epitopes in immunotherapies." (PMID 37829505, 2023). "A single-cell RNA sequencing study revealed that cancer-associated fibroblasts expressing CD74 could modulate the immune response in pancreatic tumors by activating CD4+ T cells." (PMID 37653101, 2023). "CD4+ T cells are a key mediator of immune suppression in pancreatic cancer." (PMID 36239683, 2023). "The most common CD molecules mentioned in the publications included in this review of breast and pancreatic cancers were CD4 and CD8, in the context of treatment; while others such as CD19 and CD16 were also assessed in several studies, both for treatment as well." (PMID 37181043, 2023). "The study revealed that the concurrent administration of Korean red ginseng alongside adjuvant chemotherapy led to an increased count of CD4+ lymphocytes and a higher CD4+/CD8+ T lymphocyte ratio following chemotherapy in individuals diagnosed with bile duct or pancreatic cancer." (PMID 37958889, 2023). "As an important contributor of the immunosuppressive microenvironment in pancreatic cancer, MDSCs induce the inactivation of NK cells, CD4+ and CD8+ T cells by inhibition of lymphocyte activity, recruitment of Tregs and expression of immunosuppressive checkpoint molecules." (PMID 37064113, 2023). "And there was no clear association for pancreatic cancer prognosis in only three subgroups (Enriched CD4+ memory T cells, Enriched Macrophages and Decreased Mesenchymal stem cells)." (PMID 37773521, 2023). "Importantly, TSLP-activated WT CD4+ Th2 cells suppressed P48-Cre LSL-KrasG12D p53f/f pancreatic tumor growth compared with TslprKO CD4+ T cells in Tslptg TslprKO recipient mice." (PMID 35657353, 2022).
pancreatic cancer (continued). "In addition, the proportion of peripheral CD4+ T cells positively correlated with the survival of patients with metastatic pancreatic cancer, and the proportion of peripheral CD8+CD122+ T cells was associated with early mortality (< 90 days)." (PMID 36333670, 2022). "It was also found that high levels of M2 macrophages and Treg cells in tumor-infiltrating cells were significantly associated with poorer survival, while high levels of CD4+ T, CD8+ T and M1 macrophages were significantly associated with higher survival rate in pancreatic cancer patients." (PMID 36405738, 2022). "Similarly, in pancreatic cancer, it was also confirmed that IL-10 stimulates the conversion of CD4+ T cells to CD4+ FoxP3+ Tregs cells." (PMID 35159208, 2022). "Additionally, we showed that FBW7 expression was positively associated with CD4 and CD8 cell infiltration in RCC, liver cancer and pancreatic cancer." (PMID 35081978, 2022). "Furthermore, the glucose levels in inactive CD4+ T cells co-cultured with DKK3-overexpressing pancreatic cancer BxPC-3 cells were higher than normal control group." (PMID 34391478, 2021). "Our study suggested that increased immune cell infiltration (especially CD4+ T cells) and tumor cell proliferation may play an opposite role in liver metastasis recurrence after pancreatic cancer." (PMID 34485300, 2021). "DKK3 alters the metabolic microenvironment of pancreatic cancer cells and further facilitates the function of CD4+ T cells which suggesting that DKK3 may have a therapeutic potential in pancreatic cancer." (PMID 34391478, 2021). "SAFB might improve clinical outcomes via the migration of CD4+ T cells into the pancreatic tumor microenvironment." (PMID 34490033, 2021). "In pancreatic cancer, memory CD4+ T cells are closely related to gemcitabine resistance." (PMID 34589112, 2021). "In this study, we hypothesized that DKK3 may affect the proliferation and function of CD4+ T cells by regulating glucose metabolism in pancreatic cancer cells to investigate the value of DKK3 on aerobic glycolysis in pancreatic cancer cells." (PMID 34391478, 2021). "Additionally, PSC-conditioned media attracted increased numbers of cytotoxic CD8+ and CD4+ T cells in vitro, suggesting that PSCs are important regulators of immune cell infiltration into the pancreatic tumor stroma." (PMID 32865617, 2020). "In a study of patients undergoing RFA for locally advanced pancreatic cancer, Giardino and colleagues showed that CD4+, CD8+ and effector memory T cells increased from day 3 and myeloid antigen presenting dendritic cells increased at day 30, suggesting activation of the adaptive response." (PMID 32748119, 2020). "Conversely, the present findings have demonstrated as a proof of principle that tripartite treatment allow infiltration of CD4 and CD8a and other immune activators including effector T-cells and turns the pancreatic tumor to a hot tumor which is more responsive to tripartite treatment." (PMID 32326142, 2020). "In addition, high TME-derived STAT3 activity correlates with an immunosuppressive TME in pancreatic cancer, characterized by CD4 T cell and monocyte infiltration and high copy number variation burden." (PMID 31796877, 2019). "High infiltration of CD4 T cells in pancreatic tumors correlates with extended survival." (PMID 31068602, 2019). "To determine whether the MDSC and Treg cell interactions are present also in the human pancreatic cancer, we have studied the expression of different immune markers (CD4, CD8, CD15, CD11b, Foxp3) in a cohort of PDAC patients." (PMID 32038621, 2019). "Thus, our results indicate that PD1-CD28 fusion protein-transduced CD4+ T cells have the potential to overcome the PD-1-PD-L1 immunosuppressive axis in pancreatic cancer and non-Hodgkin lymphoma." (PMID 30214445, 2018). "In addition, CD4+ T-cell mesothelin epitopes were also shown to induce IFN-γ production in peripheral blood from patients with pancreatic cancer." (PMID 29854291, 2018).
pancreatic cancer (continued). "Myeloid-derived suppressor cells (MDSCs), which reveal immunosuppressive in tumor microenvironment via inhibition of CD4+ T cell proliferation, accumulate in tumor cells and peripheral blood as the disease is progressed or in advanced stages of pancreatic cancer." (PMID 30453583, 2018). "Results from a heterotopic mouse model of PDAC using nonmetastatic murine Pan02 cancer cells and an orthotopic xenograft mouse model using metastatic human Panc-1 cancer cells revealed that pancreatic cancer expresses CCL5 to recruit CD4+Foxp3+ Treg cells, which have high levels of CCR5." (PMID 29379802, 2017). "In addition to induction of IL-10 expression in Foxp3+ Treg cells, TGFβ from CD4+Foxp3+ Treg cells and pancreatic cancer also stimulates transcription factor Foxp3 expression in Foxp3− naïve T cells, leading to differentiation of Foxp3+ Treg cells." (PMID 29379802, 2017). "Interestingly, HF10 antigens were detected in pancreatic carcinoma over 300 days after treatment with infiltration of CD4+ and CD8+ T cells, which enhanced the immune response." (PMID 28770166, 2017). "In digested pancreatic tumor samples, 10.8 % of CD4+ TIL and 7.9 % of CD8+ TIL expressed 4-1BB." (PMID 27777771, 2016). "Despite upregulation of 2B4 on T cells with increasing myeloma burden, which has also been observed on CD8 and CD4 T cells in a mouse pancreatic cancer model, blockade of PD-L1 plus the ligand for 2B4, CD48, did not provide any additional benefits over PD-L1 blockade alone." (PMID 25614821, 2015). "This suggests that there are more CD4+ T cells in the pancreatic tumor compared to normal tissue." (PMID 25415223, 2014). "For that sake, short term T cell lines were generated from PBMCs of 16 healthy controls, 15 patients with benign pancreatic diseases and 25 patients with pancreatic carcinoma and Mesothelin-specific CD4+ and CD8+ T cell responses were analysed using intracellular cytokine assays for IFN-γ." (PMID 24520352, 2014). "The high levels of TGFβ expression by this murine pancreatic tumor cell line, and the longer interval (seven weeks) of in vivo co-residence of naïve CD4 T cells and tumor, may explain their clearcut but different findings." (PMID 22112546, 2011). "Aim of this study was to evaluate whether the Th2 polarization of CEA-specific CD4+ T cells from pancreatic cancer patients is stable or can be reverted by immunomodulating cytokines." (PMID 19798410, 2009). "Moreover, we showed that B7-H3 gene expression in pancreatic cancer tissues significantly correlated with the levels of CD4 and CD8." (PMID 20035626, 2009). "Gene expressions were markedly increased in pancreatic cancer tissues compared to normal pancreatic tissues (CD4: 150 transcripts ± 28.1 in pancreatic cancer vs. 52 transcripts ± 12.4 in normal pancreas; CD8: 171 transcripts ± 30.2 in pancreatic cancer vs. 39 transcripts ± 6.4 in normal pancreas)." (PMID 20035626, 2009). "Interestingly, we observed a positive correlation between BAP1 expression and the level of tumor-infiltrating immune cells, including CD8+ T cells, NK cells, CD4+ T cells, macrophage, neutrophil and dendritic cells, but not Myeloid-derived suppressor cells in pancreatic cancer tissues." (PMID 39350280, 2024). "Furthermore, a study on pancreatic cancer reported that a close proximity of immunosuppressive IL10+ myelomonocytes to cytotoxic granzyme-B+ CD8+ T-cells instead of PD-1+ CD4 + T-cells was associated with shorter survival in non-neoadjuvant treated patients." (PMID 38386105, 2024). "The proportion of CD4+ memory T cells, CD4+ resting T cells, M0 macrophages, and M1 macrophages was considerably elevated in the three subtypes, illustrating that these cells may have a fundamental function in immunotherapy of pancreatic cancer." (PMID 36567857, 2022).
pancreatic cancer (continued). "The presence of intratumoral CD8+ T cells as well as the polarization of conventional CD4+ T (Tconv) cells toward a Th1 phenotype were both associated with prolonged survival in human PDAC, whereas Th2 cells promoted tumor progression in murine pancreatic cancer." (PMID 36509285, 2022). "However, pancreatic cancer cells inhibit the proliferation and migration of CD4+ T cells." (PMID 29670543, 2018). "In HGSOC, prostate cancer, and pancreatic cancer cases with HRD phenotype, CD4+ Treg cells in the TME and circulating CD4+ Treg cells account for a higher proportion of T cells." (PMID 40830526, 2025). "Targeting mesothelin (MSLN) improved neoantigen vaccine efficacy in pancreatic cancer by reducing apCAFs, which disrupted the conversion of naive CD4+ T cells into Tregs and enhanced the infiltration of IFN‐γ+CD4+ and GZMK+CD8+ T cells." (PMID 39887656, 2025). "Combined blockade of IL-6 and PD-L1 inhibits pancreatic cancer progression and prolongs survival by increasing the infiltration of intratumoral effector CD8+ T cells and promoting the conversion of circulating CD4+ T cells to the Th1 phenotype." (PMID 40948749, 2025). "For instance, in the phase 2 PRINCE trial for metastatic pancreatic cancer, survival benefit with the CD40 agonist sotigalimab correlated with baseline immune signatures of an active APC compartment and robust CD4 + T cell infiltration." (PMID 41182434, 2025). "The bioactivity of ectopically expressed PU.1 in CD4+ and CD8+ CAR T cells was addressed by monitoring PU.1 target genes before and after 2 days of stimulation of anti-CEA CAR T cells with CEA+ BxPC-3 pancreatic tumor cells." (PMID 39123467, 2024). "Another finding suggested that apigenin increased CD4/CD8 T cells and decreased T regulatory cells in pancreatic cancer cell." (PMID 38515580, 2024). "CD4+ CD25+ Tregs, recruited into the TME by pancreatic cancer cells, perform a significant role in immunosuppression during pancreatic cancer progression." (PMID 39195299, 2024). "Firstly, previous study showed that tumor organoids express MHC class II proteins in pancreatic cancer, suggesting that the tumor cells present MHC class II antigens for CD4+ T cells." (PMID 38954022, 2024). "Pancreatic cancer exhibits high expression of ITGA2, however, the expression of CD4 and CD8 gradually decreases with tumor progression, rendering immunotherapy for advanced pancreatic cancer ineffective." (PMID 37881431, 2023). "The relationship between the expression of ITGA2, CD4 and CD8 in pancreatic cancer tissues and the clinicopathological features." (PMID 37881431, 2023). "This study evaluated the overall survival (OS) of pancreatic cancer patients by analyzing the expression of ITGA2, CD4, and CD8." (PMID 37881431, 2023). "To investigate the effect of ITGA2 on the immune microenvironment of pancreatic cancer, we conducted immunohistochemistry to detect the expression of ITGA2, CD4+T cells, and CD8+T cells in tumor tissues." (PMID 37881431, 2023). "The study included clinicopathological data of pancreatic cancer and the expression of ITGA2, CD4+T and CD8+T cells in tumor tissues for Cox model analysis." (PMID 37881431, 2023). "GM-CSF stimulates an anti-tumor immune response through priming CD4+ and CD8+ T cells, in part through recruiting and activating dendritic cells, and is currently being investigated for use in pancreatic cancer vaccines." (PMID 37342194, 2023). "To validate expression of the TCF1 protein, we performed co-immunofluorescent staining on primary human pancreatic cancer samples and found that TCF1 was expressed on CD4+ and CD8+ T cells." (PMID 36239683, 2023). "For primary pancreatic tumors, late stage (III-IV) PDA demonstrated higher ICOS-PD-1-CD127hiCD8+ (C12) and CD4+ T cells (C10) compared to early stage PDA tumors (Stage I-II)." (PMID 36798126, 2023).